KDM5B (lysine demethylase 5B)
Diseases named in the same sentence as KDM5B in open-access papers (continued):
Sharing a sentence is not in itself a finding about the gene and the disease.
tumor (continued). "Importantly, at least some KDMs (LSD1, KDM4A, KDM5B, KDM6B) are among the key modulators of stemness/pluripotency markers in head and neck cancer stem cells, which suggests their potential significance for tumor recurrence." (PMID 35326475, 2022). "This study suggests a promising KDM5B‐targeted therapy for HCC patients and also proposes that a KDM5B/miR‐448/YTHDF3/ITGA6 axis is involved in the occurrence and development of this cancer, which could constitute an important tumour‐related molecular mechanism." (PMID 33829656, 2021). "The KDM5 subfamily (also known as JARID1 subfamily) consists of four members, KDM5A (JARID1A), KDM5B (JARID1B), KDM5C (JARID1C) and KDM5D (JARID1D) whose deregulation in various kinds of cancer has been widely documented to contribute significantly to tumor initiation and progression." (PMID 31060229, 2019). "We evaluated the effect of KDM5B expression on tumor cell motility with or without KDM5B knockdown." (PMID 26917489, 2016). "Moreover, we also found higher expression levels of both E2F1 and E2F2 in clinical tumor tissues where KDM5B was overexpressed, than in non-neoplastic tissues (P = 0.0009 and P = 0.0002, respectively)." (PMID 20226085, 2010). "Therefore, aberrant overexpression of KDM5B in any tumor, compared to corresponding non-neoplastic tissues, make it an ideal molecular target with potential for cancer detection and as a therapeutic target." (PMID 20226085, 2010). "KDM5A and KDM5B have been indicated to be carcinogenic in numerous studies, while KDM5C and KDM5D may function as tumor suppressors, although the evidence is conflicting which may be due to the specific tumor microenvironment and different experimental conditions." (PMID 38769556, 2024). "KDM5B expression was upregulated in HCC cells and tissues but not in the periphery of the tumour tissue." (PMID 33604316, 2021). "Lastly, we found a strong negative correlation between KDM5B expression and STING expression in The Cancer Genome Atlas (TCGA) tumor samples." (PMID 30080846, 2018). "Expression levels of PYGO2, KDM5B, PHF20L1, and ZMYND8 were also significantly higher in tumor samples compared to that in non-tumor breast tissue." (PMID 28055972, 2017). "Indeed, KDM5B protein expression was increased significantly as early as 2 h after hypoxia induction in SGC7901 and 4 h in BGC823 cells but not the non-tumor gastric epithelial GES-1 cells." (PMID 34977006, 2021).
cancer (150 papers, 2006 to 2026). A tumor composed of atypical neoplastic, often pleomorphic cells that invade other tissues. "Recent evidence indicates that KDM5B is frequently found upregulated in various human cancers functioning as an oncogene and associates with human cancers closely." (PMID 38789418, 2024). "KDM5B acts a transcriptional repressor and has primarily been implicated in the pathogenesis of cancer." (PMID 37788244, 2023). "KDM5B is associated with malignant proliferation and metastasis of cancer cells, and it has the potential to be a prognostic factor for lung cancer." (PMID 37220590, 2023). "Genome sequencing of human tumors unveiled a common mutation, amplification and overexpression of KDM5B in many cancer types." (PMID 35428764, 2022). "Increased levels of KDM5A and KDM5B have been associated with chemoresistance in cancer and appear to contribute to an increase in cancer cell proliferation." (PMID 35563709, 2022). "KDM5B is upregulated in several tumors and cancer-derived cell lines, which seems to be associated with resistance to genotoxic stress." (PMID 33859667, 2021). "The deregulated expression of KDM5B has been implicated in numerous cancer types, including breast, lung, skin, prostate, testis, and liver." (PMID 32751840, 2020). "Abnormal expression and functions of KDM5B have been implicated in several cancer types including PCa." (PMID 33245716, 2020). "This is in line with the previous finding of an increase of KDM5B regulating H3K4me3 and loss of H3K27me3 which was associated with poor prognosis and drug resistance in different cancer types." (PMID 29492189, 2018). "While the role of KDM5A remains less characterized, KDM5B is specifically implicated in the survival of cancer “stem cells”." (PMID 25329053, 2014). "However, the machinery underlying the KDM5B enhances cancer drug resistance is obscure and are still being elucidated." (PMID 38789418, 2024). "In addition, the nonepigenetic roles of other histone demethylase members, such as KDM5A and KDM5B, are implicated in the repair of DNA, prevention of replication stress caused by hydroxyurea (HU), and development of HU-tolerant persister cancer cells." (PMID 36982384, 2023). "Interestingly, overexpression of KDM5A or KDM5B is also implicated in several cancers progression and drug resistance." (PMID 37034668, 2023). "However, there is evidence that KDM5B is implicated in numerous pro-oncogenic mechanisms in many different types of cancer, including the hypoxic response, immune evasion and PI3/AKT signalling." (PMID 37152294, 2023). "Expression of KDM5B is increased in several cancer types, including PCa, with elevated expression implicated in multiple pro-oncogenic mechanisms in many cancer types." (PMID 37152294, 2023). "Interestingly, overexpression of KDM5A or KDM5B is also implicated in the progression and drug resistance of several cancers (16, 54, –56)." (PMID 37722046, 2023). "In other cancer entities, KDM5B is inconsistently associated with survival." (PMID 35650266, 2022). "We further examined the mutational landscape of the KDM5B gene across a spectrum of cancers." (PMID 33245716, 2020). "High KDM5B expression was associated with cancer cell growth and tumorigenicity." (PMID 27974677, 2017). "KDM5B is significantly upregulated in various cancers, particularly breast cancer, and its oncogenic properties make it a promising target for personalized drug therapy." (PMID 40764352, 2025). "Together, these data suggest that KDM5B depletion sensitizes the cancer cells to chemotherapeutic agents and decreases drug resistance." (PMID 38789418, 2024). "We recently showed that a predicted KDM5B amino-terminal truncated isoform (KDM5B-NTT) is indeed expressed in several cancer cell lines." (PMID 39000010, 2024). "As expected, the level of KDM5B were higher in PDAC cancer tissues than in normal adjacent tissues, in contrast, the m6A level of KDM5B were lower." (PMID 38789418, 2024).
cancer (continued). "KDM5B is robustly expressed and endowed with oncogenic activity in multiple cancers, such as prostate, hepatocellular, and breast cancers." (PMID 38842683, 2024). "In the literature, various roles of KDM5B have been reported in cancers, and the histone demethylase KDM5B has presented itself as a therapeutic target for cancer therapy." (PMID 39497715, 2024). "KDM5B is considered an oncogene that promotes the proliferation and invasion of many malignant tumors." (PMID 39039611, 2024). "Although the study by Zhang and colleagues focused mainly on the effect of KDM5B knockout on the anti-cancer immune response, the authors showed that KDM5B recruits and stabilizes SETDB1 to silence its targets, including REs." (PMID 39519018, 2024). "KDM5A and KDM5B are overexpressed in many cancers and play a role in the response to genomic damage and drug tolerance." (PMID 39000010, 2024). "As KDM5B-NTT is relatively abundant in different cancer cell lines, it is important to understand its effects on cell function." (PMID 36697763, 2023). "KDM5B histone demethylase is overexpressed in many cancers and plays an ambivalent role in oncogenesis, depending on the specific context." (PMID 36697763, 2023). "ETV has the potential to be beneficial in treating various types of cancer, particularly due to its ability to inhibit KDM5B and potentially PARP-1 as well." (PMID 38004468, 2023). "KDM5A and KDM5B are amplified or overexpressed in a range of cancers, including breast, ovarian, skin, and lung." (PMID 36803422, 2023). "Pathway analysis identified genes expressed higher in tumors with high KDM5B (Q4) to be involved in cancer pathways, including PCa." (PMID 37152294, 2023). "This study identifies KDM5B as histone modifier that is crucial for AR regulated gene expression in castrate sensitive PCa, but whose role in advanced cancers is altered." (PMID 37152294, 2023). "The roles of KDM5C and KDM5D in malignancies are less defined, although, in contrast to KDM5A and KDM5B, it is generally reduction of these proteins that is observed in cancers, most notably renal carcinomas." (PMID 37800333, 2023). "Previous research has indicated that KDM5B plays an essential role in the apoptosis of cancer cells." (PMID 37185734, 2023). "The relationship between KDM5A, KDM5B and tumorigenesis appears to be primarily oncogenic, with a range of cancers showing increased expression of either of these two paralogs." (PMID 37800333, 2023). "Of the family members, KDM5B is overexpressed in an array of cancers including prostate, breast, and bladder carcinoma, and is also expressed in slow-growing cancer stem cells in melanoma." (PMID 36975603, 2023). "Specific lysine histone demethylases (KDM5), such as KDM5B, play a crucial role in gene expression and epigenetic regulation in several types of cancer." (PMID 38004468, 2023). "KDM5B has attracted extensive attention and is regarded as a promising drug target of cancer therapy." (PMID 35428764, 2022). "KDM5A and KDM5B play important roles in various physiological and pathological events ranging from the maintenance of homeostasis to the development of cancer." (PMID 36509829, 2022). "KDM5B has been implicated in several cancers, including NSCLC, and was recently described as a therapeutic target for cancer therapy." (PMID 36233212, 2022). "Recognizing these differences, we aimed to focus on comprehensively refining the roles of KDM5A and KDM5B in the context of development and cancer progression." (PMID 36509829, 2022). "RNA-sequencing data for cancer cells depleted of KDM5A or KDM5B demonstrate the heterogeneity of their target genes." (PMID 36509829, 2022). "KDM5B also induces a cancer stem cell-like phenotype by activating the c-MET signaling pathway in NSCLC cells." (PMID 35805040, 2022). "Conversely, KDM5B inhibition impairs DNA repair, leading to the sensitization of cancer cells to radiation." (PMID 35805040, 2022).
cancer (continued). "Pan-cancer analysis of KDM5B expression was performed in The Cancer Genome Atlas (TCGA) database, and we found that KDM5B was highly expressed in ESCC patients." (PMID 35333349, 2022). "KDM5B promotes cancer stem cell-like properties by elevating the expression of CD113, Oct4A, KLF4, and Nanog." (PMID 35326475, 2022). "Both KDM5A and KDM5B have been shown to be key determinants of a dynamic, phenotypic heterogeneity in cancer, defining differentiation, proliferation and responsiveness of cell populations to therapeutic intervention." (PMID 35899196, 2022). "Overall, KDM5B plays a key role in cancer progression by promoting cancer stemness, epithelial–mesenchymal transition, the cell cycle, DNA repair, and intratumoral heterogeneity." (PMID 35805040, 2022). "KDM5B, upregulated in aggressive phenotypes of multiple cancer types, has been the target of numerous pharmacological inhibitors, but none have advanced to the clinic due to off-target effects and toxicity." (PMID 36497341, 2022). "KDM5B has also been reported as an oncogene in other types of cancers, including hepatocellular carcinoma, esophageal cancer, gastric cancer, colorectal cancer, oral cancer, Ewing sarcoma, glioma, acute lymphoblastic leukemia, and chronic myeloid leukemia." (PMID 35805040, 2022). "In another study, cells with high expression of KDM5B were identified as cancer stem-like cells showing high expression of CD44 and ALDH1 and increased activity of PI3K." (PMID 35326475, 2022). "We also highlight both the possibility of targeting KDM5A and KDM5B to improve cancer treatment and the limitations that must be overcome to increase the efficacy of current drugs." (PMID 36509829, 2022). "KDM5A and KDM5B histone-demethylases are overexpressed in many cancers and have been involved in drug tolerance." (PMID 34184733, 2021). "As KDM5B was upregulated to play an oncogenic role in multiple cancers, many chemical inhibitors of KDM5B have been extensively evaluated for their potential in targeted therapy of human cancer." (PMID 34977006, 2021). "In this respect, it was recently shown that inhibition of KDM5B demethylase activity increases the radio-sensitivity of cancer cell lines upregulating KDM5B, suggesting that the catalytic activity of KDM5 is important in this context." (PMID 33859667, 2021). "Overall, the analysis of genomic amplifications in KDM5B gene supports an oncogenic role of KDM5B in many human cancers including PCa." (PMID 33245716, 2020). "Our molecular docking investigations show that decitabine, entecavir, abacavir, penciclovir, and DZNep have the potential to be repurposed as KDM5B inhibitors to treat various types of cancers." (PMID 32751840, 2020). "Surprisingly, KDM5B is overexpressed (or shows the trend of overexpression) in many human cancers in addition to PCa." (PMID 33245716, 2020). "The suppression of KDM5B expression showed a significant reduction in cancer cell growth via the E2F/RB1 pathway." (PMID 32751840, 2020). "The leading role of KDM5B oncogene in tumorigenesis and cancer progression is well established in various malignancies and is therefore, considered as a potential therapeutic target." (PMID 32751840, 2020). "KDM5B inhibitors have also been reported to overcome radioresistance in cancer cells by preventing the demethylation of H3K4 at the sites of double-strand breaks induced by radiation." (PMID 33245716, 2020). "Considering the central role of KDM5A and KDM5B for the development of cancer persisters 2, 3, it is very likely that the observed shift toward oxidative phosphorylation is, at least in part, necessary to supporting epigenetic remodeling." (PMID 32483452, 2020). "We anticipate that these studies will stimulate further research in considering drug repurposing approaches to target KDM5B, and to discover novel therapies for various cancers." (PMID 32751840, 2020).
cancer (continued). "This review attempts to comprehend, as thoroughly as possible, the oncogenic role of KDM5B in major cancer types and the drug repurposing potential of some known small molecules by targeting KDM5B’s catalytic domain through molecular docking studies." (PMID 32751840, 2020). "Although many small molecule inhibitors of KDM5B have been identified so far, their possible clinical application in cancer treatment is a work in progress." (PMID 32751840, 2020). "Consistently, recent studies have indicated that HIF1α increased the expression of histone demethylase KDM5B in cancer cells." (PMID 33304897, 2020). "Published reports support a role for KDM5B in the maintenance or differentiation of normal and cancer stem cells." (PMID 31776402, 2019). "KDM5B is overexpressed in certain cancers, and has led to interest in the development of KDM5B inhibitors for clinical use60,61." (PMID 31776402, 2019). "In support of this possibility, KDM5A and KDM5B have been shown to interact with the NuRD complex in cancer cells." (PMID 30940185, 2019). "We tested the possibility that while KDM5B and its inhibitors likely regulate other targets, HEXIM1 is a critical mediator of the anti-cancer effects of KDM5B inhibitors." (PMID 31805991, 2019). "KDM5A and KDM5B induces the growth of cancer cells, reduces the expression of tumor suppressor genes, facilitates the acquired tolerance of cancer-fighting drugs, and maintains tumor-initiating cells." (PMID 30064416, 2018). "Previous studies, including ours, have shown that KDM5 family histone demethylases, especially KDM5A and KDM5B, are highly expressed and promote tumorigenesis in multiple cancer types." (PMID 30080846, 2018). "KDM5 demethylation activity is involved in regulating cell differentiation and proliferation (KDM5A and KDM5B) and has been related to disease states, especially cancer." (PMID 28827149, 2017). "Since the KDM5B--BF-1--PAX9 interaction played an important role in embryogenesis, it was possible KDM5B exerted similar functions in cancer development as well." (PMID 27974677, 2017). "We report comprehensive biochemical, structural and cellular studies on the interaction of TCA cycle intermediates with KDM5B, which is a current medicinal chemistry target for cancer." (PMID 28827149, 2017). "In this review, we will summarize recent advances in our understanding of the regulation and function of KDM5B in development and cancer." (PMID 27974677, 2017). "This projects MALAT1 as a mediator of KDM5B oncogenic potential and highlights the critical role of this microRNA, lncRNA and histone demethylase in cancer cell motility and metastatic colonization." (PMID 26917489, 2016). "Several preclinical studies suggest inhibition of KDM5B histone demethylase can suppress tumorigenesis and provide strong rationale for development of their inhibitors for use in cancer therapy." (PMID 26911146, 2016). "Considering the growing evidence for an important function of KDM5B proteins in cancer, it becomes an attractive target for chemotherapeutic drug design." (PMID 26911146, 2016). "Recent reports suggesting a role for KDM5B in regulation of the EMT program in cancer stem cells and interaction of KDM5B with EMSY, prompted us to investigate the SIN3A-KDM5B interaction." (PMID 26460951, 2015). "JARID1B, also known as KDM5B, is a histone lysine demethylase, identified as an oncogene in many cancer types." (PMID 25951238, 2015). "We also examined the functional effects of KDM5B on the growth of cancer cell lines treated with small interfering RNAs (siRNAs)." (PMID 20226085, 2010). "We showed that reduction of KDM5B expression resulted in suppression of cell growth of cancer cells, through co-regulation of the E2F/RB1 cell cycle regulation pathway, and possibly the promotion of apoptosis of cells remaining in sub-G1 phase." (PMID 20226085, 2010). "We found that KDM5B enhances cancer cell proliferation and cancer cells stemness." (PMID 38789418, 2024).